CRP (C-reactive protein)
Diseases named in the same sentence as CRP in open-access papers (continued):
Sharing a sentence is not in itself a finding about the gene and the disease.
cancer (continued). "On the contrary, the authors did not observe any relationship between sP2X7R and CRP plasma levels in patients with cancer, a condition generally characterized by low-grade chronic inflammation." (PMID 38069064, 2023). "GPS is a clinical scoring system for cancer patients, defined by two liver-derived acute-phase proteins (APPs), C-reactive protein (CRP; positive APP) and albumin (negative APP)." (PMID 37803016, 2023). "An interesting review on CRP and cancer has demonstrated that plasma CRP is not selective for any specific cancer type, CRP > 10 mg/L have been correlated with active and advanced cancer conditions or can be markers of complications." (PMID 37873776, 2023). "In patients not diagnosed with cancer, 15% had elevated CRP, 33% had elevated IL‐6 and 25% had elevated YKL‐40." (PMID 36440611, 2023). "A combination of CRP, IL‐6, YKL‐40, CEA and CA 19‐9 was the best predictor of cancer (AUC of 0.77)." (PMID 36440611, 2023). "IMMUNEPOTENT CRP (ICRP) is a bovine dialyzable leukocyte extract (DLE) obtained from disrupted spleen; it has shown immunomodulatory properties and cytotoxic activity against cancer cell (Arnaudov, 2017; Kirkpatrick 2000)." (PMID 37223080, 2023). "A meta-analysis showed that CRP has a non-linear relationship with all-cause mortality and CVD mortality and a linear relationship with cancer and non-cardiovascular mortality." (PMID 35571939, 2022). "In recent years, the CRP-to-ALB ratio (CAR) has emerged as a novel biomarker for predicting the mortality and prognosis of critically ill patients with coronary artery disease, severe sepsis, or cancer." (PMID 36457873, 2022). "Four patients were excluded from both groups: in the PPSNP group, three patients had metastasized cancer and one was an hs-CRP outlier; in the non-PPSNP group, two patients had metastasized cancer and two a chronic neurological disease." (PMID 35408848, 2022). "GPS, based on CRP and ALB has been widely adopted as a systemic inflammatory and nutritional index, which indicated as a prognostic score not only for postoperative survival in ESCC but also for survival in various cancers." (PMID 35300627, 2022). "A recent meta-analysis summarized 54 studies and suggested that peripheral blood inflammatory markers (CRP, TNF and IL-6) were significantly related to cancer-related DepS and might be helpful for management of DepS in the cancer patients." (PMID 36615742, 2022). "There were no changes in the HR for RA nor CRP in the Step3 model including additional adjustments for previous cancer or chronic respiratory disease." (PMID 36329101, 2022). "Although CRP serum levels were not different among patients and controls, only the cancer group showed median CRP values above the normal range (0–0.5 mg/dL)." (PMID 35454855, 2022). "Compared to a healthy control group, treatment-naïve cancer patients with different malignant disorders had increased NET formation, which correlated to plasma levels of the inflammatory marker CRP and the cardiac disease biomarkers NT-proBNP and sTNFR1, in agreement with the mouse data." (PMID 35309730, 2022). "The underlying mechanism is that inflammatory processes are involved in regulating the relationship between social support and cancer mortality, with patients at higher levels of social support and satisfaction having lower levels of inflammatory factors, including IL-6, TNF-α, CRP, and VEGF." (PMID 36091116, 2022). "In cancer patients, CRP correlated with BNP independent of the age, creatinine level, hypertension, and body mass index." (PMID 35872912, 2022). "A recently appreciated notion of the dynamic nature of CRP, referring to its ability to undergo a nonproteolytic conformational transformation, extended the comprehension of its role in cancer-related inflammation amplification and regulation." (PMID 35629255, 2022).
cancer (continued). "Some biomarkers such as C-reactive protein, α1-acid glycoprotein, neutrophils Neutrophil-lymphocyte ratio (NLR) and platelet-lymphocyte ratio (PLR) are closely related to the prognosis of cancer patients and have potential clinical significance for monitoring the prognosis of cancer patients." (PMID 36684205, 2022). "Similarly, previous studies have shown that CRP, GNRI, ALI, and LCR can predict the prognosis of patients with cancer." (PMID 35866083, 2022). "There was also a significant positive correlation between plasma BNP and serum CRP levels in cancer patients (R = 0.360, p < 0.01) but not in those without." (PMID 35872912, 2022). "ESPEN guidelines indicate that patients with low cancer activity and no inflammatory response, defined as serum CRP < 10 mg/dL, should receive nutritional support because their nutritional status can deteriorate rapidly." (PMID 35276861, 2022). "Both CRP and LHR showed good survival predictions in patients with cancer." (PMID 35752767, 2022). "The risk posed by inflammation is not specific to post-cancer diagnosis as elevated CRP in childhood was predictive for cancer mortality." (PMID 35206642, 2022). "Due to hypoxia and necrosis in cancer, CRP levels will arise as a nonspecific inflammatory response." (PMID 36532648, 2022). "We investigated the effect of combining CRP and LHR on the prognosis of patients with cancer and found that patients with high CRP and high LHR had a significant increase in HR [model 4: HR (95% CI) =1.77 (1.49–2.05), P<0.001] than those with low CRP and low LHR." (PMID 35752767, 2022). "We analyzed the prognostic value of the individual biomarkers in elderly patients with cancer and survival curve results showed that patients with high CRP, low GNRI, high ALI, and low LCR had worse OS than those with low CRP, high GNRI, high ALI, and high LCR (all P < 0.001)." (PMID 35866083, 2022). "C-reactive protein (CRP) is a highly sensitive but non-specific acute phase protein that has been widely used to predict the biological behavior of patients with cancer." (PMID 36718344, 2022). "Participants with incident cancer had higher CRP concentration (2.7 ± 3.6 mg/L) than those without incident cancer (2.4 ± 3.3 mg/L)." (PMID 36117174, 2022). "CRP and LHR showed good survival predictive values in patients with cancer." (PMID 35752767, 2022). "Some authors suggest that cancer should not be used as a positive criterion for inflammation and that serum CRP should be determined additionally." (PMID 35276861, 2022). "The prognostic value of the C-reactive protein to albumin ratio (CAR) among older adults with cancer is not known." (PMID 34830936, 2021). "CRP levels have been reported to be significantly more increased in metastatic than nonmetastatic cancer patients, highlighting a particular importance of CRP as a systemic metabolite in advanced metastatic cancer disease." (PMID 33562331, 2021). "Increased circulating levels of CRP have been found in cancer cachexia patients compared with weight stable cancer patients and non-cancer patients." (PMID 33925872, 2021). "The PSA always went down from pre-radiation levels (or remained stable), so the cancer was being killed or at least suppressed, while the CRP did not change." (PMID 34926085, 2021). "The CRP albumin ratio has also been shown predictive of mortality in patients without cancer for example in patients having systemic lupus with serious community-acquired infection or in critically ill patients." (PMID 34944774, 2021). "Patients diagnosed with cancer had significantly lower levels of hemoglobin, albumin and iron, and significantly higher levels of leukocytes, ESR, GGT and ALP, ferritin, TSH, LDH and CRP." (PMID 34555091, 2021). "CRP and α-glycoprotein were also negatively correlated with CYP3A activity and cancer patients with significant acute-phase response may have reduced CYP3A drug metabolism, which may have implications for the safety and efficacy of chemotherapy." (PMID 34867341, 2021).
cancer (continued). "Moreover, serum C‐reactive protein (CRP) and albumin are important inflammatory markers, and the C‐reactive protein:albumin ratio (CAR) is a prognostic factor in many cancers." (PMID 33434414, 2021). "Among several inflammatory prognostic markers, CRP is the most commonly studied, while mGPS was revealed to have prognostic value in cancer, independent of tumor site." (PMID 34945079, 2021). "IMMUNEPOTENT CRP (ICRP) acts as an immunomodulator and can be cytotoxic to cancer cells." (PMID 33531687, 2021). "The Glasgow prognostic score (GPS), a scoring system that combines CRP and albumin levels, is a prognostic score for cancer patients that is independent of the stage of the disease." (PMID 34445197, 2021). "Common markers in both COVID-19 and cancer are carbohydrate antigens (CA) 125 and 153, carcinoembryonic antigens (CEA), human epididymis protein 4 (HE4), C-reactive protein (CRP), and cytokeratin-19 fragment (CYFRA21-1); these markers are increased in both COVID-19 and cancer." (PMID 33912588, 2021). "The presence of systemic inflammatory response, as evidenced by high C-reactive protein (CRP), low albumin (Alb), and high neutrophil-lymphocyte ratio (NLR), also has independent prognostic value in patients with advanced cancer." (PMID 33757453, 2021). "Hence, general inflammation markers like C-reactive protein (CRP), leucocytes, or lymphocytes have been studied and shown some potential as prognostic markers in several cancers, even though results have been conflicting." (PMID 33509254, 2021). "Several retrospective studies describe a reduction in C-reactive protein (CRP)-levels after EPA supplementation, however evidence in cancer patients is ambiguous as increased inflammatory markers could also be caused by increased cell damage." (PMID 34073158, 2021). "The present prospective study of 232 patients with MBD in the extremities from various primary cancer types showed that elevated plasma IL-6, but not CRP and YKL-40, was an independent prognostic parameter for short OS." (PMID 34200156, 2021). "Decreased albumin level was reported in patients with cancer cachexia compared with weight stable cancer patients or non-cancer controls, and in another study, it was shown to negatively correlate with CRP levels." (PMID 33925872, 2021). "In men but not in women, common inflammation markers of advanced cancer (low hemoglobin and high values of thrombocyte count, C-reactive protein, erythrocyte sedimentation rate, and alkaline phosphatase) were inversely correlated with 25(OH) D." (PMID 33975557, 2021). "Laboratory measures (C-reactive protein, troponin, lymphocytes, platelets) were not available for all included patients but were similar among cancer and non-cancer patients when available." (PMID 34771446, 2021). "Previous studies have examined the prognostic significance of inflammatory response markers, including neutrophil-to-lymphocyte ratio (NLR), C-reactive protein (CRP)-to-albumin ratio (CAR), platelet-to-lymphocyte ratio (PLR), and albumin-to-globulin ratio (AGR), for various cancers." (PMID 34115873, 2021). "GPS is a scoring system that combines CRP and albumin, and is a prognostic score for cancer patients independent of the stage of the disease." (PMID 33808957, 2021). "IMMUNEPOTENT CRP (ICRP) is a mixture of low-molecular-weight substances obtained from bovine spleen that has immunomodulatory and cytotoxic effects on cancer cells, produced by the Laboratory of Immunology and Virology of the Autonomous University of Nuevo León, Mexico." (PMID 34638242, 2021). "Another systematic review reported that a large proportion of studies examined CRP as a prognostic marker of cancer incidence or survival; however, MR did not highlight any evidence of causality." (PMID 34386016, 2021). "CRP was seen to be an independent predictor of cancer-specific survival but not overall survival in uni- and multivariable (HR 1.01 (1.00–1.02); p = 0.028) analyses of non-irradiated patients." (PMID 32316975, 2020).
cancer (continued). "D‐dimers, lactic dehydrogenase (LDH) and C‐reactive protein (CRP), as parameters of systemic inflammation, were elevated at admission and during hospitalization, but did not reveal significant differences between cancer and noncancer patients." (PMID 32931637, 2020). "In other types of cancer stages the differences in CRP values were not significant against the control." (PMID 30828780, 2020). "The pooled odds ratio and hazard ratio (HR) with 95% confidence interval (CI) were applied to evaluate the difference in overall survival (OS), progress‐free survival (PFS), and cancer‐specific survival (CSS) between patients with high CRP and those without." (PMID 33201589, 2020). "Unfortunately, cytokine and CRP assessments are not routine in the clinic or clinical practice for cancer patients, and thus, challenge their practicality to assist in the daily physician decision process." (PMID 32371869, 2020). "CRP (> 9.8 mg/L) also exhibited a high value in the diagnosis of EOC and can be used as a diagnostic marker for this cancer—especially in the absence of other diseases." (PMID 33208875, 2020). "Another study showed a significant association between cholinesterase activities including BChE with IL-6 and TNF-α but not with CRP in frail elderly patients without cancer." (PMID 32375339, 2020). "In contrast, CRP levels were not able to predict cancer death after correction for apoB/apoA-I ratio." (PMID 31936330, 2020). "In our executed study, CAR demonstrated a discrimination ability superior to that of other scores based on inflammation, namely CRP, mGPS, NLR, and PLR, in resectable OSCC patients—consistent with findings reported by previous research executed among patients with other types of cancer." (PMID 32587804, 2020). "Recently, CRP, NLR, and GPS/mGPS have attracted attention as prognostic factors in cancer." (PMID 32716955, 2020). "Interestingly, the C-reactive protein or CRP, is a major acute protein considered for low grade systematic inflammation in chronic disease like cancer, cardiovascular and T2DM." (PMID 32694996, 2020). "CRP was not a predictor of overall survival (HR 0.99, 95% CI 0.98–1.01) nor cancer-specific survival in irradiated patients (HR 0.94, 95% CI 0.94–1.02)." (PMID 32316975, 2020). "Elevated C-reactive protein (CRP) (p <0.001), urea (p = 0.002), ferritin (p = 0.01), troponin (p = 0.009), and low albumin (p = 0.02) at presentation were predictors of mortality in the cancer cohort." (PMID 33330085, 2020). "Though numerous studies have assessed biomarkers of mortality in cancer patients, no other study has to their (and our) knowledge assessed CRP and PA levels in the last 2 months before patients’ death." (PMID 32209087, 2020). "After more complete control for socioeconomic confounding, CRP and fibrinogen do not predict cancer mortality in most subpopulations." (PMID 33243216, 2020). "CRP has been reported to be associated with both the malignant potential of neoplasms and physical cachexia, and several studies have shown that cancer patients with elevated serum CRP levels had a worse prognosis than those without." (PMID 33176752, 2020). "The relationship between CRP and cancer mortality was not significant in the NHANES 1999–2002 cohort, regardless of socioeconomic status (0.22–0.99 mg/dL: 95%CI: 0.55–1.59) (> 0.99 mg/dL: 95%CI: 0.92–2.42)." (PMID 33243216, 2020). "CRP alone is unlikely to be a cancer-specific prognostic predictor, but in patients with inflammation, it was possible to predict cancer-specific prognosis when evaluated in combination with SII." (PMID 32676164, 2020). "When CRP levels were added in the analysis, the apoB/apoA-I ratio, but not apoB levels, remained significantly related to cancer mortality (Q4 = HR: 1.17; 95% CI: 1.09–1.25)." (PMID 31936330, 2020).
cancer (continued). "C-reactive protein (CRP) is a predominant protein of the acute phase response; its blood levels have long been used as a minimally invasive index of any ongoing inflammatory response, including that occurring in cancer." (PMID 33324413, 2020). "In this study, large tumor size, high WBC count, low Hb count, high CRP level, and a high LDH level were shown to be significant predictive factors for malignant tumors, and the presence of three or more predictive factors was an appropriate threshold with the maximum Youden’s index." (PMID 32183216, 2020). "Serum PD‐L1 levels were significantly correlated with neutrophil counts and CRP, albumin, and SCC‐Ag levels; in addition, correlations were observed among serum PD‐L1 level, advanced‐stage cancer, and lymphocyte counts (statistical significance notwithstanding)." (PMID 31865635, 2020). "However, the albumin / CRP ratio, also considered as the Inflammatory-Nutritional Index (INI), is seldom reported with a prognosis of cancer." (PMID 31164099, 2019). "Our study indicates that GPS score based on serum CRP and albumin levels may show inflammatory status; it might also have prognostic value in ICCU patients as in cancer patients." (PMID 31096693, 2019). "It has also been found that elevated CRP in cancer patients correlates with the expression of IL-6 and IL-6 receptors in cancer cells in the absence of apparent inflammation." (PMID 31038863, 2019). "In present study of Chinese NSCLC patients, a dose-dependent relationship was also found between CRP and death regardless of cancer stage." (PMID 31148582, 2019). "In fact, the C-reactive protein (CRP – an acute phase protein and a biomarker of inflammation) is increasingly considered to be involved In systemic response to inflammation, and lies on the path of biological plausibility for cancer induction." (PMID 31035959, 2019). "Female cancer survivors presented with higher platelet and leukocyte counts, lower low density lipoprotein cholesterol/high density lipoprotein cholesterol (LDL/HDL) ratio and higher C-reactive protein (CRP) and fibrinogen levels compared to male cancer survivors." (PMID 31882836, 2019). "CRI parameters, including C-reactive protein (CRP), platelet-to-lymphocyte ratio (PLR), and neutrophil-lymphocyte ratio (NLR), are widely used in cancer patients to guide treatment and predict prognosis." (PMID 31632844, 2019). "Our findings are compatible with the fact that CRP is a better indicator of (cancer) mortality rather than of short-term morbidity." (PMID 30150729, 2018). "Given that the inflammatory response plays a vital role in cancer, it is not surprising to find increased CRP levels in various cancers." (PMID 29668751, 2018). "Furthermore, CRP is a non-specific marker of systemic inflammation, so it is not clear whether the elevated baseline CRP levels in fatigued subjects was secondary to other causes of inflammation, which include cancer itself." (PMID 29849049, 2018). "For systemic inflammatory response estimation, serum levels of white blood cells, neutrophils, lymphocytes, platelets, C-reactive protein (CRP) and albumin, either alone or in several combinations, have been used as prognostic factors in various malignant solid tumors." (PMID 30509242, 2018). "Soluble P-selectin as well as tissue factor, D-dimer, C-Reactive Protein, platelet, and leukocyte counts has been proposed as promising biomarkers that may be predictive of VTE in cancer." (PMID 29692812, 2018). "Exclusion criteria were inflammation (C-reactive protein (CRP) ≥ 5 mg/L), bleeding, or cancer." (PMID 29596361, 2018). "Another study reported that cytokine levels and the CRP level are clinically relevant for CRC progression, and that measurement of TNF-α serum levels may help identify early cancer progression among patients with CRC." (PMID 29949857, 2018).